GLIPR1 (GLI pathogenesis related 1)
Diseases named in the same sentence as GLIPR1 in open-access papers (continued):
Sharing a sentence is not in itself a finding about the gene and the disease.
cancer (18 papers, 2012 to 2025). A tumor composed of atypical neoplastic, often pleomorphic cells that invade other tissues. "CAPS2 (Calcyphosine 2) (average methylation 26%, p = 0.005) and GLIPR1L2 (GLI pathogenesis-related 1) (average methylation 30%, p = 0.008), both were previously discussed in the group due to hypomethylation in PD-L1 high-expressing carcinomas." (PMID 38791918, 2024). "The differential expression pattern is possibly due to the epigenetic status of GLIPR1 in different cancers." (PMID 28771580, 2017). "WDR77 and PRMT5 are ubiquitously re-expressed in lung hyperplasia and cancer and conversely, GLIPR1 expression is significantly down-regulated during lung tumorigenesis." (PMID 26988096, 2016). "Functional studies revealed both growth suppression and proapoptotic activities for GLIPR1 in multiple cancer cell lines." (PMID 26988096, 2016). "The discrepancy in the GLIPR1 expression between the two genistein groups indicated that the effects of genistein are dose-dependent, and genestien only inhibits cancer at a high concentration." (PMID 25385471, 2015). "The data above indicated GLIPR1 as a membrane protein is a promising target for cancer therapy." (PMID 38368374, 2024). "In addition, GLIPR1 slows down the growth of cancer cells and increases the secretion of CCL5, which leads to the activation of immune cells." (PMID 35479325, 2022). "Despite a growing body of literature pointing to a role for GLIPR1 in cancer, little is known of the normal function of GLIPR1 and of how disruption might contribute to cancer initiation or progression." (PMID 24010123, 2013). "Since carcinomas and abnormal findings were not confirmed in the liver, RT-qPCR was performed to examine the expression levels of Glipr1, Clec12a, and Phlda3 in 3-, 6-, 12-, 24-, and 32–34-month-old mouse livers." (PMID 37648885, 2023).
GLIPR1 also shares sentences with these, for which no sentence is quoted: acute lymphoblastic leukemia (2 papers); colorectal cancer (2); bladder tumors (1); brain cancer (1); brain tumor (1); chronic myeloid leukemia (1); HIV-1 infection (1); infection (1); large cell lung cancer (1); liver cancer (1); oligodendroglioma (1); osteosarcoma (1); plasma cell tumours (1); type I diabetes (1); viral infections (1).